PDIA3P1 (protein disulfide isomerase family A member 3 pseudogene 1)
Synonyms: GRP58P; formerly PDIA3P
Gene: Transcribed processed pseudogene on chromosome 1 (147,178,113 to 147,179,622, forward strand). Ensembl gene ENSG00000180867.
Diseases named in the same sentence as PDIA3P1 in open-access papers:
PDIA3P1 is named in the same sentence as 20 diseases in open-access papers, as found by Europe PMC text mining. Sharing a sentence is not in itself a finding about the gene and the disease. The quoted sentences say what the papers report.
glioma (9 papers, 2020 to 2026). A benign or malignant brain and spinal cord tumor that arises from glial cells (astrocytes, oligodendrocytes, ependymal cells). "Similar to a study in glioma cells, the results showed that PDIA3P1 was mainly localized in the cytoplasm of KYSE-150 and Eca-109 cells." (PMID 38254118, 2024). "PDIA3P1 is upregulated in various malignant tumors, including lung cancer, oral squamous cell carcinoma, liver cancer, glioma and multiple myeloma." (PMID 38254118, 2024). "LncRNA PDIA3P1 sponges miR-124-3p to activate NF-κB pathway to facilitate mesenchymal transition in glioma." (PMID 37941005, 2023). "In vitro and in vivo assays revealed that knockdown of PDIA3P1 resulted in decreased resistance to TMZ in glioma cells; in contrast, overexpression of PDIA3P1 resulted in increased resistance of glioma cells to TMZ." (PMID 35836243, 2022). "We demonstrated that NEF inhibits TMZ-induced upregulation of PDIA3P1 and enhances the sensitivity of glioma cells to TMZ treatment." (PMID 35836243, 2022). "Based on bioinformatics analysis, we found that expression of PDIA3P1 was higher in recurrent gliomas than in primary gliomas." (PMID 35836243, 2022). "Taken together, these findings indicate that PDIA3P1 promotes glioma cell resistance to TMZ both in vitro and in vivo." (PMID 35836243, 2022). "Combining in vitro and in vivo assays, we further confirmed that PDIA3P1 reduces the TMZ sensitivity of glioma cell lines." (PMID 35836243, 2022). "LncRNA PDIA3P1 promoted glioma mesenchymal transition by competitively binding to miR-124-3p in a hypoxic environment to regulate RELA expression and activate the downstream NF-κB pathway." (PMID 34178684, 2021). "Transwell assay showed that PDIA3P1 overexpression promoted the migration and invasion capacity of glioma cells, while PDIA3P1 knockdown inhibited the capacity." (PMID 32127518, 2020). "After filtering out the low expressing genes according to GSE45301 and TCGA datasets, we found that PDIA3P1 was highly expressed and obviously increased in hypoxia-treated glioma cells, as well as the tumor samples according to TCGA-LGG and TCGA-GBM datasets." (PMID 32127518, 2020). "In this study, we found that PDIA3P1 expression was closely related to tumor degree, transcriptome subtype, and prognosis in glioma patients." (PMID 32127518, 2020). "We first performed FISH and subcellular fractionation to determine PDIA3P1 distribution in glioma cells." (PMID 32127518, 2020). "To investigate the biological role of PDIA3P1 in glioma, we analyzed 70 samples from the top (n = 35) and bottom (n = 35) according to their PDIA3P1 level in the TCGA-GBM database." (PMID 32127518, 2020). "PDIA3P1 upregulation increased the protein level of MES markers, whereas PDIA3P1 knockdown inhibited their expression in glioma cells." (PMID 32127518, 2020). "In summary, we revealed that hypoxia-induced factor 1 directly bound to the promotor region and upregulated the expression of PDIA3P1, which promotes cell migration and invasion through the PDIA3P1-miR-124-3p-RELA axis in human gliomas." (PMID 32127518, 2020). "Collectively, these results showed that PDIA3P1 is enriched in the cytoplasm and directly sponges miR-124-3p in glioma cells." (PMID 32127518, 2020). "Next, we knocked down HIF1A and determined the expression levels of PDIA3P1 and miR-124-3p in glioma cells." (PMID 32127518, 2020). "Result showed that only miR-124-3p expression was decreased in PDIA3P1 overexpressing glioma cells and increased in the knockdown counterparts." (PMID 32127518, 2020). "Further analysis using The Cancer Genome Atlas (TCGA) and the Chinese Glioma Genome Atlas (CGGA) database showed that high PDIA3P1 expression represents a more malignant tumor type and results in poorer outcomes in glioma patients." (PMID 32127518, 2020). "In vitro study revealed that overexpression of PDIA3P1 enhanced the migration and invasion capacity of glioma cells, while knockdown of PDIA3P1 induced the opposite effect." (PMID 32127518, 2020).
glioma (continued). "Here, we investigated the clinical significance, biological function, and mechanisms of protein disulfide isomerase family A member 3 pseudogene 1 (PDIA3P1) in hypoxia-induced glioma MES transition." (PMID 32127518, 2020). "To assess the clinical significance of PDIA3P1 in glioma patients, we evaluated the correlation between PDIA3P1 expression and patient clinicopathologic characteristics using the TCGA database." (PMID 32127518, 2020). "Glioma stem cells (GSCs) were used to determine the effect of PDIA3P1 on the GBM subtype." (PMID 35836243, 2022). "Hypoxia-induced PDIA3P1 promoted mesenchymal transition via sponging of miR-124-3p in glioma." (PMID 36009075, 2022). "PDIA3P1 overexpression or knockdown changed the migration and invasion capacity of glioma cells." (PMID 32127518, 2020). "PDIA3P1 upregulation in hypoxia-cultured glioma cells was reversed when HIF1A was inhibited." (PMID 32127518, 2020). "Results showed that glioma cell lines possessed higher PDIA3P1 levels than NHA cells." (PMID 32127518, 2020). "Results confirmed that PDIA3P1 knockdown or miR-124-3p overexpression inhibited the protein level of p65 and its phosphorylated form, while PDIA3P1 overexpression or miR-124-3p inhibition increased their expression in our glioma cell models." (PMID 32127518, 2020). "Our findings verified that RELA is a direct target of miR-124-3p, suggesting that PDIA3P1 might induce glioma MES transition by activating the NF-κB pathway." (PMID 32127518, 2020). "Consequently, the PDIA3P1-miR-124-3p-RELA axis is a possible target for glioma therapy." (PMID 34178684, 2021). "In addition, hypoxia increased PDIA3P1 expression in all 4 glioma cell lines, as was expected." (PMID 32127518, 2020). "Mechanistically, PDIA3P1 promoted PMT by disrupting the C/EBPβ/MDM2 complex to inhibit the ubiquitination of C/EBPβ, enabling glioma cells to obtain stronger TMZ therapy resistance." (PMID 35836243, 2022). "High PDIA3P1 expression is correlated with EMT, extracellular matrix disassembly, and angiogenesis and can promote the migration and invasion of glioma cells." (PMID 33995499, 2021). "In this study, we revealed that HIF-1 heterodimer mediated PDIA3P1 upregulation, and miR-124-3p downregulation promoted the MES transition of gliomas through activating the NF-κB pathway." (PMID 32127518, 2020). "Mechanically, PDIA3P1 sponges miR-124-3p to upregulate RELA expression and, in turn, activates the downstream NF-κB pathway, which promotes a highly invasive mesenchymal (MES) transition of glioma cells." (PMID 33995499, 2021). "In addition, a positive correlation between the expression of PDIA3P1 and RELA was confirmed in glioma samples." (PMID 32127518, 2020). "Further studies revealed that PDIA3P1 functions as a ceRNA, sponging miR-124-3p to modulate RELA expression and activate the downstream NF-κB pathway, thus promoting the MES transition of glioma cells." (PMID 32127518, 2020). "In conclusion, PDIA3P1 is a crucial link between hypoxia and glioma MES transition through the PDIA3P1-miR-124-3p-RELA axis, which may serve as a prognostic indicator and potential therapeutic target for glioma treatment." (PMID 32127518, 2020). "Collectively, this study demonstrated that PDIA3P1 is a crucial link between hypoxia and glioma MES transition, thus it may serve as a potential candidate for predicting prognosis and as a target for therapy in glioma patients." (PMID 32127518, 2020).
esophageal squamous cell carcinoma (6 papers, 2024 to 2026). Esophageal squamous cell carcinoma (ESCC) is a type of esophageal carcinoma (EC) that can affect any part of the esophagus, but is usually located in the upper or middle third. "PDIA3P1 expression in human esophageal squamous cell carcinoma (ESCC) tissues and cell lines was detected by quantitative real-time polymerase chain reaction (qRT-PCR)." (PMID 38254118, 2024). "This study reveals a new mechanism by which PDIA3P1 regulates the progression of esophageal squamous cell carcinoma (ESCC)." (PMID 40470706, 2025). "In esophageal squamous cell carcinoma (ESCC), WTAP mediates m6A modification on the lncRNA PDIA3P1, which is then recognized by IGF2BP1 to enhance its stability." (PMID 41522342, 2026). "lncRNA PDIA3P1 serves as a ceRNA of miR-152-3p to prevent degradation of GLUT1, therefore promoting glycolysis, enhancing elevated lactate production and accelerating esophageal squamous cell carcinoma (ESCC) tumor progression." (PMID 41361062, 2025).
hepatocellular carcinoma (6 papers, 2019 to 2024). A malignant tumor that arises from hepatocytes. "While previous studies have linked PDIA3P1 to promoting proliferation and invasion in hepatocellular carcinoma cells, its role in PE remains unexplored." (PMID 38715918, 2024). "In hepatocellular carcinoma (HCC), higher PDIA3P1 level is associated with poorer recurrence-free survival." (PMID 34947885, 2021). "Previous studies have found that PDIA3P1 is highly expressed in hepatocellular carcinoma and regulates nuclear factor kappa light chain enhancer of activated B cell signaling and chemotherapy resistance through PDIA3P1-miR-125/124-TRAF6." (PMID 38254118, 2024).
glioblastoma (5 papers, 2020 to 2026). The most malignant astrocytic tumor (WHO grade IV). "New research has uncovered that the overexpression of lncRNA PDIA3P1 is linked to the glioblastoma temozolomide resistance in cancer cell lines." (PMID 41362671, 2026). "Furthermore, PDIA3P1 promotes the proneural-to-mesenchymal transition in glioma stem cells, thereby increasing the resistance of glioblastoma to temozolomide treatment." (PMID 41362671, 2026). "PDIA3P1 can further sponge miR-124-3p, which is found to inhibit angiogenesis by targeting NRCP1 in glioblastoma." (PMID 32992718, 2020).
multiple myeloma (4 papers, 2020 to 2026). "A recent study investigated the lncRNA protein disulfide isomerase family A member 3 pseudogene 1 (PDIA3P), known for its high expression in multiple myeloma and association with the survival rates of patients with this disease." (PMID 41362671, 2026).
liver cancer (3 papers, 2020 to 2026). An epithelial or non-epithelial malignant neoplasm that arises from the liver. "Silencing the PDIA3P1 in liver cancer cells reduced doxorubicin's effectiveness in triggering cell death, as indicated by alterations in the expression of apoptosis-related markers." (PMID 41362671, 2026). "Interestingly, down-regulation of the PDIA3P1 was observed in CD133-negative liver cancer cells, suggesting its potential involvement in regulating cancer stem cell functions." (PMID 41362671, 2026).
esophageal cancer (2 papers, 2024 to 2026). A primary or metastatic malignant neoplasm involving the esophagus. "Implicating flow cytometric analysis and sphere formation assays to examine the side population (SP), CD271+ CD44+ cells, and sphere formation, they also reveal that PDIA3P1 enhances CSC features of esophageal cancer." (PMID 41431719, 2026). "Functionally, higher PDIA3P1 expression promoted cell proliferation, invasion, and metastasis and inhibited apoptosis in esophageal cancer." (PMID 38254118, 2024). "In this study, we investigated the regulation of esophageal cancer stem cell properties by the interaction of PDIA3P1 with proteins." (PMID 38254118, 2024). "Our results suggest that PDIA3P1 positively regulates CSC properties by promoting OCT4 expression, indicating that PDIA3P1 might be a promising therapeutic target for esophageal cancer." (PMID 38254118, 2024). "The mechanism of high expression of PDIA3P1 in esophageal cancer is still unclear." (PMID 38254118, 2024). "In this way, PDIA3P1 may be a potential therapeutic target in treating esophageal cancer." (PMID 41431719, 2026). "Together, PDIA3P1 and OCT4 establish a positive feedback network that regulates the CSC characteristics of esophageal cancer." (PMID 41431719, 2026).
tumor (10 papers, 2019 to 2025). "High PDIA3P1 expression was associated with tumor differentiation (P = 0.026), TNM stage (P = 0.015), and T grade (P = 0.032)." (PMID 40470706, 2025). "High PDIA3P1 expression was associated with tumor differentiation (P = 0.047), TNM stage (P = 0.006) and T grade (P = 0.039)." (PMID 38254118, 2024). "Despite its established role in ESCC progression, the precise molecular mechanisms through which PDIA3P1 drives tumor malignancy remain elusive." (PMID 40470706, 2025). "KEGG and Gene Ontology (GO) analyses of the downregulated peak genes in the promoter region of PDIA3P1‐KD cells indicated that these genes are involved in multiple signaling pathways related to tumor progression." (PMID 40470706, 2025). "As examined by the tumor sphere culture, the siRNA-induced downregulation of PDIA3P1 significantly impaired sphere formation and reduced the sphere size of TE-1 and Eca-109 cells." (PMID 38254118, 2024). "We found that the oncogene PDIA3P1, and tumor-suppressor RRN3P3, promote the RNA and protein expression of their targeted immune-involved genes AKT1 and EZH2 via miR-34a-5p and miR-26b-5p, respectively." (PMID 36438489, 2022). "We experimentally validate the oncogene PDIA3P1, and tumor-suppressor RRN3P3, which promote the RNA and protein expression of their targeted immune-involved genes AKT1 and EZH2 via miR-34a-5p and miR-26b-5p, respectively." (PMID 36438489, 2022). "M6A-seq identified two m6A peaks on oncogene pseudogene PDIA3P1 and one m6A peak on tumor-suppressor pseudogene RRN3P3, and the m6A-LAIC-seq data showed that full-length RNAs of pseudogenes were significantly enriched in m6A positive fraction." (PMID 36438489, 2022). "Bioinformatics analyses of public databases combining qRT–PCR results indicated that expression of PDIA3P1 was upregulated in TMZ-resistant cell lines and predicted a higher risk of tumor recurrence." (PMID 35836243, 2022). "PDIA3P1 is overexpressed and its expression is connected with tumor degree and transcriptome subtype." (PMID 34947885, 2021). "H&E staining showed obscure tumor borders and tenuous ECM in PDIA3P1 overexpressing samples, however, samples in the control group exhibited a clear tumor border and dense ECM." (PMID 32127518, 2020). "Bioluminescence imaging 10 days after injection showed that mice bearing PDIA3P1 overexpressing U87MG cells exhibited significantly higher tumor viability than control mice." (PMID 32127518, 2020). "Moreover, interrogation of the Gene Expression Omnibus (GEO) database for ESCC indicated that the PDIA3P1 level is higher in tumor tissue than in normal tissues." (PMID 38254118, 2024). "Similarly, high PDIA3P1 levels in U87MG cells resulted in a larger invasion area in the 3D tumor spheroid invasion assay and a longer migration distance in U251 cells in the wound healing assay." (PMID 32127518, 2020). "In this study, PDIA3P1 is highly expressed in ESCC, produces more lactate by regulating glycolysis, and the increased lactate upregulates lactylation levels to drive tumor progression." (PMID 40470706, 2025). "In contrast, overexpression of PDIA3P1 in sensitive cell lines (U251 and LN229) resulted in a significant increase in IC50 values and counteracted the inhibitory effect of TMZ on tumor cell growth." (PMID 35836243, 2022). "To exclude the possibility that the observed function of PDIA3P1 is limited to cell lines, we performed further validation using GSC20, which is isolated from a GBM patient derived tumor." (PMID 35836243, 2022). "In other studies, Sun and colleagues demonstrated that PDIA3P1 is overexpressed in OSCC and promotes tumor cell proliferation by absorbing miR-185-5p25." (PMID 32127518, 2020). "Targeting p38α may block the stress response of tumor cells, preventing TMZ-induced upregulation of PDIA3P1." (PMID 35836243, 2022).
tumor (continued). "Compared to HPV negative, patients with HPV positive had significantly higher expressions of oncogene pseudogenes (SDHAP1, SDHAP3, DDX12P, CLUHP3, and RRN3P3), but there was no prominent difference in the expressions of tumor-suppressor pseudogenes (PDIA3P1, LDHAP4, LDHAP7, EEF1A1P6, and EEF1A1P11)." (PMID 36438489, 2022). "Knockdown of PDIA3P1 in resistant cell lines (U118MG and U87MG) resulted in a notable reduction in IC50 and further inhibition of the tumor cell growth rate upon TMZ treatment." (PMID 35836243, 2022). "H&E-stained mouse brain sections showed that knockdown of PDIA3P1 greatly reduced tumor invasiveness, with or without TMZ treatment, whereas overexpression of PDIA3P1 promoted tumor invasiveness." (PMID 35836243, 2022).
cancer (6 papers, 2021 to 2026). A tumor composed of atypical neoplastic, often pleomorphic cells that invade other tissues. "The dysregulated expression of several lncRNAs, such as CRNDE, TINCR, and PDIA3P1, has been associated with chemotherapy resistance in several human cancers, highlighting that lncRNAs might represent attractive molecular targets for cancer treatment." (PMID 35717675, 2022). "PDIA3P1 is upregulated in multiple cancer types and following treatment with DNA-damaging chemotherapeutic agents such as doxorubicin (Dox)." (PMID 34947885, 2021). "Further experimental studies, involving both overexpression and knockdown of lncRNA PDIA3P1, revealed that this lncRNA protected cancer cells from undergoing doxorubicin-induced apoptosis, thereby enabling tumor xenografts to grow more rapidly and become more resistant to doxorubicin treatment." (PMID 41362671, 2026). "The lncRNA protein disulfide isomerase family A member 3 pseudogene 1 (PDIA3P1) has been shown to promote cancer stem cell properties; however, its mechanism of action remains unclear." (PMID 38254118, 2024). "Importantly, PDIA3P1 promoted cancer stem cell properties in ESCC." (PMID 38254118, 2024). "Our study demonstrates that the positive feedback loop between PDIA3P1 and OCT4 plays a key role in adjusting cancer stem cell properties of ESCC." (PMID 38254118, 2024).
PDIA3P1 also shares sentences with these, for which no sentence is quoted: lung carcinoma (2 papers); oral squamous cell carcinoma (2); cervical cancer (1); congenital hypothyroidism (1); digestive tumors (1); endometrial cancer (1); gastric cancer (1); head and neck squamous cell carcinoma (1); nasopharyngeal carcinoma (1); osteosarcoma (1); papillary thyroid cancer (1).